CXCL8 (C-X-C motif chemokine ligand 8)
Diseases named in the same sentence as CXCL8 in open-access papers (continued):
Sharing a sentence is not in itself a finding about the gene and the disease.
tumor (continued). "The meta-analysis indicated that increased CXCL8 mRNA level was significantly associated with advanced tumor stage in NSCLC patients (pooled OR = 1.52, 95% CI 1.13–2.05), especially in ADC patients (pooled OR = 1.71, 95% CI 1.12–2.61)." (PMID 29636079, 2018). "Our study indicated that CXCL8 both at the mRNA and protein level was associated with the high tumor burden of ADC." (PMID 29636079, 2018). "Taken together, our study was consistent with a previous study that DACH1 was negatively correlated with tumor progression, whereas high CXCL8 expression was associated with unfavorable prognosis of NSCLC patients." (PMID 29636079, 2018). "In this study, in vitro assays reaffirm that one impact of tumor-derived CXCL8 from PTEN-deficient tumor cells is to enhance chemotactic migration of macrophages." (PMID 26799286, 2016). "IL-8/CXCL8 is associated with tumor angiogenesis, metastasis and poor prognosis in several cancer types." (PMID 26078356, 2015). "In other words, downregulation of IL-6 secreted by endothelial cells inhibits phosphorylation of STAT3 in tumor cells, which will then secrete less angiogenic factors (e.g. CXCL8) causing a decrease in tumor microvessel density and tumor growth." (PMID 24533454, 2014). "Tumor-associated DC can directly drive tumor angiogenesis through the release of pro-angiogenic cytokines such as TNFα, CXCL8, and osteopontin." (PMID 24782982, 2014). "Concerning CXCL8, its expression seems to be associated with tumor size, lymph node, distant metastases, and poor prognosis in patients with esophageal squamous cell carcinomas." (PMID 24971349, 2014). "Since CXCR1 and CXCR2 receptors are expressed on cancer cells, endothelial cells, neutrophils, and tumor-associated macrophages, the synthesis and secretion of CXCL8 from tumor cells affects the tumor microenvironment." (PMID 24224100, 2013). "Disease stage (P<0.001) and tumour infiltrate CXCL8 positivity (P=0.007) were associated with enhanced RFS in multivariate Cox regression analysis." (PMID 21285972, 2011). "The majority of the tumour cores (65.4%) expressed positive CXCL8 immunoreactivity within the tumour-associated inflammatory infiltrate." (PMID 21285972, 2011). "CXCL8-positivity in the tumour infiltrate was associated with a statistically significant reduction in the risk of disease recurrence (hazard ratio: 0.55, CI: 0.36–0.85, P<0.001)." (PMID 21285972, 2011). "Conversely, increased expression of CXCL8 in the inflammatory cell infiltrate of the tumour tissue is associated with a favourable prognosis in this cohort of stage II and stage III CRC tissues." (PMID 21285972, 2011). "For example, elevated tumour CXCL8 levels have been associated with increased tumour size, depth of infiltration, disease stage and liver metastasis, as well as a shorter overall survival time in CRC." (PMID 21285972, 2011). "Of note, it has been shown that CXCL8 in PDAC is associated with tumor genesis by promoting angiogenesis and metastasis but not with survival." (PMID 20214814, 2010). "Similarly, CXCL8 (C-X-C motif chemokine ligand 8) is typically associated with tumor progression, angiogenesis, and metastasis." (PMID 41382114, 2025). "Moreover, tumor cells induce tumor-associated neutrophils to release neutrophil extracellular traps (NETs) through autocrine signaling via IL-8/CXCL8, CXCR1/CXCR2 agonists, G-CSF, and TGF-β pathways." (PMID 40563367, 2025). "Reduction of CXCL8 expression attenuated tumor-associated angiogenesis." (PMID 40260916, 2025). "One of the main effective cell types associated with the CXCL8/IL-8 axis is macrophages, especially tumor-associated macrophages (TAMs), which play crucial roles in disrupting the progression of cancer through various mechanisms, including cytokine secretion and immunosuppression." (PMID 39905539, 2025).
tumor (continued). "SLC2A3 exhibited a strong correlation with inflammatory gene expression, and its upregulation induces an inflammatory microenvironment through CXCL8-mediated activation of tumor-associated macrophages, subsequently promoting tumor cell progression and metastasis." (PMID 38778609, 2025). "Furthermore, neutrophils exposed to soluble factors derived from SMAD4-deficient CRCs exhibit upregulated CXCL8 expression, thereby amplifying the inflammatory signaling within the tumor microenvironment." (PMID 40943634, 2025). "Of particular interest is the enrichment of M0 and M2 macrophages, which resonates with a seminal study demonstrating that radiotherapy induces a distinct, PD‐L1+ tumor‐associated myeloid subset that co‐upregulates protumorigenic factors (IL‐6, CXCL8) and immune checkpoints." (PMID 41473739, 2025). "Elevated CXCL8 serum level is associated with the severe tumor load and distant metastasis." (PMID 38213742, 2024). "Other studies have also implicated CXCL8 in tumor progression." (PMID 39409924, 2024). "Furthermore, the BRAF mutation is associated with the production of CXCL8, a proinflammatory chemokine that can promote tumor proliferation, angiogenesis, and metastasis." (PMID 37014331, 2023). "In conclusion, tumour necrosis is associated with high circulating CXCL8 concentrations, suggesting that CXCL8 could contribute to the pro-tumour systemic effects of tumour necrosis." (PMID 37031328, 2023). "Consequently, both systemic and tumor-associated CXCL8 is associated with resistance to or reduced clinical benefit of chemotherapy, radiotherapy, molecularly targeted therapy, or immune checkpoint inhibition therapy like blockade of PD-1 or PD-L1." (PMID 36725964, 2023). "Notably, it has been shown that the serum CXCL-8 level seemed to be a more accurate diagnostic marker for PC compared to classic tumor markers like CA 19-9 or CEA." (PMID 37835833, 2023). "In addition, we identify the cell type subsets of the Galectin 7B (LGALS7B)-expressing malignant cells and CXCL8-expressing fibroblasts, demonstrating that their abundance in tumor tissue is associated with unfavorable prognostic outcomes." (PMID 36828832, 2023). "Furthermore, we report that high CCL20 and CXCL8 serum levels were associated with microvascular invasion, a characteristic of advanced tumor stages." (PMID 36982370, 2023). "PD-L1 has promoted the growth of the cells, their ability to release the pro-metastatic chemokine CXCL8 and to invade; all these functions were elevated by exposure to PD-1 in vitro, and have led to increased tumor growth and metastasis in a T cell-deficient mouse model system." (PMID 37830552, 2023). "The present study hypothesizes that tumor sEV CXCL8 mRNA levels may be used to monitor recurrence risk during remission and monitor tumor senescence." (PMID 37215082, 2023). "Furthermore, CXCL8 can recruit CXCR2-expressing tumor-associated macrophages and induce an immunosuppressive M2 phenotype into the tumor microenvironment, as demonstrated e.g. in a murine model for pancreatic cancer." (PMID 36725964, 2023). "In addition, Glut3 overexpression in TNBC induces activation of M1 tumor-associated macrophages (M1-TAM) via lactate/C-X-C motif Chemokine ligand 8 (CXCL8), consequently creating an inflammatory TME that promotes CTCs metastasis." (PMID 36776368, 2022). "Consequently, ALKBH5-initiated CXCL8/IL8 induction improves tumor-associated macrophage infiltration and promotes tumor progression, demonstrating the impact of post-transcriptional epigenetic modifications in regulating the immunosuppressive GSC phenotype." (PMID 36212415, 2022). "CREB‐binding protein (CREBBP) was mutated more frequently in tumours with high stromal CXCL8 and when further analysis was performed on the TCGA/PanCancer Atlas dataset (n = 594) there was a significant association between CREBBP mutation and higher CXCL8 mRNA expression (p < 0.001)." (PMID 35879507, 2022).
tumor (continued). "However, CXCL8 has been associated with immunoevasion, tumor progression and resistance to (immuno)therapy in a variety of oncological settings." (PMID 36319998, 2022). "Through a single‐cell RNA sequencing analysis of a sub‐group of peripheral blood mononuclear cells (PBMCs) and tumour samples, CXCL8 mRNA was associated most strongly with the myeloid compartment of both PBMCs and tumour samples, connecting it with myeloid‐mediated immune suppression." (PMID 35394069, 2022). "Similarly, CXCL8 is an angiogenic CXCL-type chemokine implicated in tumor microenvironment neovascularization, and a strong positive correlation was found between the chemokine and CXCL1." (PMID 36164329, 2022). "CXCL8 signaling can be induced by numerous factors associated with both neoplasia and inflammation." (PMID 34072741, 2021). "A study reported that CXCL8, a pro-inflammatory chemokine, plays an important role in metastasis by associating with tumour-related inflammation and inducing the risk of OLK and OSCC, such as in the case of betel quid chewing and smoking, but the regulatory pathways are still not reported to date." (PMID 34650058, 2021). "The findings presented in this paper suggest that based on diagnostic characteristics of all proteins tested, serum CXCL8 might be used as a potential biomarker in the diagnosis of GC patients, especially in a combined assessment with classical tumor markers." (PMID 34680333, 2021). "CXCL8 was associated with tumor progression in different tumor types." (PMID 33390169, 2021). "Moreover, MSC-derived CCL2 has attracted macrophages to TNBC tumors, activating them to secrete CXCL8, thus leading to an overall increase in tumor-associated macrophages and endothelial cells." (PMID 31031757, 2019). "According to our knowledge, the present study is the first to indicate the diagnostic usefulness of CXCL-8 levels in the sera of patients with OC in comparison with the classical tumor markers (CEA and SCC-Ag) and the well-established marker of inflammation—C-reactive protein (CRP)." (PMID 30820705, 2019). "Furthermore, elevated CXCL8 expression is associated with the induction of angiogenesis as well as increased proliferation, invasion and migration of tumor cells." (PMID 32038715, 2019). "Mutation in the RAS oncogene-leading to constitutive signalling has been shown to induce the expression of CXCL8/IL8 in tumors while others have shown that tumor intrinsic mutations in the β-catenin pathway modulates T-cell infiltration by silencing the expression of DC-recruiting chemokine CCL4." (PMID 30126117, 2018). "Earlier studies indicate that CXCL8 derived from TAMs is associated with tumor progression." (PMID 29285315, 2017). "CXCL8 expression has been documented in infiltrating neutrophils, tumor-associated macrophages, tumor cells, and endothelial cells, and has been shown to regulate tumor angiogenesis, tumor cell proliferation, and metastasis potential, such as vessel invasion in HCC." (PMID 26503598, 2015). "Production of CCL17, CCL1, chemokine (C-X-C motif) ligand-13 (CXCL13) and CXCL8 (IL-8) has been shown to be associated with the activation program for M2 tumor associated macrophage (TAM), and is parts of mononuclear phagocyte-mediated regulatory circuits of innate and adaptive immunity." (PMID 26172457, 2015). "Furthermore, CXCL8 expression in patients with bronchioloalveolar carcinoma correlates positively the number of tumor-associated neutrophils as well as with a poor prognosis for the patients." (PMID 24782982, 2014). "We conclude that tumor-derived CXCL8 signaling from PTEN-deficient tumor cells increases the sensitivity and responsiveness of CaP cells to stromal chemokines by concurrently upregulating receptor expression in cancer cells and inducing stromal chemokine synthesis." (PMID 24970800, 2014).
tumor (continued). "Moreover, CXCL8 derived from tumor cells have been shown to retain DCs in the tumor resulting in deficient migration to the lymph nodes and also impaired immune response against the cancer." (PMID 22190968, 2011). "Inspired by in vitro data showing that si-CLU reduced the antioxidative stress capability and inhibited HNSCC cell viability under conditions of glucose deficiency, we further analyzed whether inhibiting CXCL8 signaling enhances the efficacy of anlotinib in suppressing HNSCC tumor growth." (PMID 39905539, 2025). "However, further studies on monocyte-derived DCs have shown that CXCL8/IL-8 can cause the migration of these cells, which may be recruited to the tumor microenvironment by CXCR2 ligands." (PMID 37686093, 2023). "Furthermore, serum CXCL-8 levels were significantly associated with M stage and tumor size." (PMID 36567905, 2022). "Therefore, CXCL8 inhibition might be a novel therapeutic strategy in targeting the tumor and the associated microenvironment." (PMID 31681401, 2019). "In addition, we also characterized whether the secretion of CXCL8 from PTEN-deficient tumor cells may affect the level of macrophage-derived TNF-α secretion." (PMID 26799286, 2016). "Thus the release of CXCL8 from the PTEN-deficient tumor cells may also potentiate the IR-induced, macrophage-derived elevation of TNF-α signaling within the microenvironment of PTEN-deficient tumors." (PMID 26799286, 2016). "Since, in the microenvironment, tumor cells are surrounded by fibroblasts, dendritic cells, tumor-associated macrophages, and other cells of lymphoid origin; CXCL8 produced by tumor cells could act on one or more of these cells, producing other cytokines, growth factors, and/or MMPs." (PMID 24224100, 2013). "Additionally, tumor cells harboring oncogenic mutations or loss of tumor suppressor genes that lead to the activation of specific signaling pathways have been shown to regulate CXCL8 or CXCR1/2 expression." (PMID 24276377, 2013). "KLF4 acts as a tumor suppressor by directly binding to the CXCL8 promoter and repressing its transcription, leading to reduced CXCL8/CXCR1/2‐mediated MDSC chemotaxis." (PMID 41532367, 2026). "Coordinated signaling between IL-1β and CXCL8/IL-8 promotes neutrophil recruitment, stimulates tumor-angiogenesis, and provokes EMT programs at invasive tumor margins, which facilitate inflammatory microenvironments that drive tumor progression." (PMID 41596524, 2026). "Mechanistically, we demonstrated that FKBP10 not only promoted EMT but also activated the MEK/ERK/ELF3 signaling axis, leading to an increased secretion of CXCL8 by tumor cells." (PMID 41694575, 2026). "Coupling in situ CIN detection with single-nucleus RNA sequencing and multiplex immunophenotyping of human EAC, we link CIN to tumor-intrinsic innate immune activation, CXCL8 expression, and myeloid cell-mediated immunosuppression." (PMID 41811963, 2026). "Among them, VEGFA and HBEGF are known to exert central roles in driving tumor angiogenesis, while CXCL8 and its related chemokines positively regulate angiogenic processes." (PMID 41514936, 2026). "Taken together, our results demonstrate a critical role of CCL2, GM-CSF, and CXCL8 in the establishment of an immune-suppressive tumor microenvironment." (PMID 41513619, 2026). "Tumor-derived CXCL8, in turn, drove macrophage M2 polarization and myeloid-derived suppressor cell (MDSC) recruitment, thereby reinforcing an immunosuppressive TIME." (PMID 41694575, 2026). "After adjusting for tumor purity, CXCL8 expression showed strong positive correlations with M2 macrophage markers (CD163, VSIG4, MS4A4A) in Gr." (PMID 41432874, 2025). "It promotes tumor proliferation and progression by regulating chemokines such as CXCL8, which also contribute to the recruitment of inflammatory cells in the tumor microenvironment, showcasing a dual role in oncogenic and inflammatory regulation." (PMID 40869212, 2025).
tumor (continued). "CXCL8 has a well-defined role in metastasis by facilitating tumor cell migration, increased vascular permeability, and new blood vessel formation." (PMID 40076892, 2025). "A recent study found that increased levels of the chemokine CXCL8 in the OC TME promote tumor growth, spread, and peritoneal metastasis." (PMID 40369674, 2025). "Subsequent immunohistochemical analysis of 12 paired CC and adjacent normal tissues confirmed that CXCL8 expression was higher in tumor tissues, consistent with GEPIA2 findings." (PMID 40596054, 2025). "CXCL8, another HERDEGs, functions in the process of recruiting immune cells to the tumor microenvironment, potentially influencing anti-tumor immunity and tumor-promoting inflammation." (PMID 40061897, 2025). "Combining PD1 blockade therapy with the inhibition of tumor-secreted CXCL8 and CXCR2-positive M2 macrophages enhances therapeutic efficacy." (PMID 40959082, 2025). "IL-8/CXCL8, produced by tumor cells, fibroblasts, and myeloid cells, drives neutrophil chemotaxis, angiogenesis, and EMT, correlating with aggressive disease and resistance to targeted and immune therapies." (PMID 41440526, 2025). "For example, CXCL8-mediated recruitment of myeloid cells limits tumor infiltration of effector T cells and shapes the immunosuppressive TME, thereby hampering cancer immunotherapy." (PMID 40861472, 2025). "Following its binding to the receptor, IL-8 (also known as CXCL8) promotes the proliferation, survival, and metastasis of cancer cells and tumour angiogenesis." (PMID 41009413, 2025). "CXCL8, alternatively referred to as interleukin-8 (IL-8), is a canonical proinflammatory and prometastatic chemokine involved in multiple stages of tumor progression." (PMID 39897048, 2025). "The tumour-biased CXCL8hi_IL1Bhi_Mac macrophages secreted proinflammatory and tumour-supporting cytokines like CXCL8, IL1B, and CCL3, inducing cancer cell growth, invasion, and metastasis." (PMID 41312167, 2025). "P.g. also manipulates inflammatory signaling in SCC-25 cells by activating NF-κB and MAPK pathways, driving tumor-associated inflammation and metastasis via upregulation of CCL20, TNFAIP6, CXCL8, TNFAIP3, TRAF5, CYP1A1, and NOD2 gene expression." (PMID 40924302, 2025). "The CXCL8/CXCR2 axis plays a significant role in tumor microenvironment (TME) remodeling, cancer plasticity, and the development of resistance to both chemotherapy and immunotherapy." (PMID 40006729, 2025). "CXCL8 (also known as IL-8), a chemokine secreted by various cells including tumor and immune cells, primarily attracts neutrophils to tumor sites." (PMID 39911388, 2025). "Given that CXCL8 enhances fibroblast activation via CXCR2 signaling, we propose that SLC6A14 regulates tumor–stroma interactions by sustaining CXCL8 secretion." (PMID 41444422, 2025). "In contrast, low-risk genes (CCL17, CXCL8, FOXP3, CCR7) inhibit tumor progression by modulating immune cell infiltration and activity." (PMID 40517358, 2025). "Neutrophils are recruited to the TME through signaling pathways that involve cytokines and chemokines such as CXCL8, granulocyte-colony stimulating factor (G-CSF), and tumor-derived factors like VEGF." (PMID 40486614, 2025). "CXCL8 promotes tumor cell proliferation, angiogenesis, and chemoresistance, while neutrophil infiltration mediated by CXCR1/2 correlates with poor clinical outcomes." (PMID 41425704, 2025). "Our study further demonstrates that the E4 subpopulation promotes tumor progression and evades immune surveillance by upregulating immune-related genes such as CXCL8, consistent with previous research findings." (PMID 40463392, 2025). "As a pro-tumor chemokine, CXCL8 plays a pivotal role in the progression, prognosis, and drug resistance across various cancers." (PMID 40596054, 2025). "RT-qPCR analysis confirmed the significant upregulation of MMP1, TFRC and CXCL8 in tumor tissues, consistent with our previous differential gene-expression studies." (PMID 40809844, 2025).